ASF1B (anti-silencing function 1B histone chaperone)
Diseases named in the same sentence as ASF1B in open-access papers (continued):
Sharing a sentence is not in itself a finding about the gene and the disease.
cancer (continued). "ASF1B expression was analyzed in pan‐cancer datasets using the UCSC Xena platform, which revealed widespread overexpression across multiple tumor types." (PMID 40944429, 2025). "In previous studies, ASF1B has been found to promote the growth of myeloma, glioma, and cancers in breast, kidney, prostate, bladder cervical, lung, liver, and stomach as an oncogene." (PMID 40041497, 2025). "In the constructed patient-specific cancer organoids, ASF1B-overexpressing organoids showed faster proliferation levels." (PMID 40041497, 2025). "These pathways are frequently dysregulated in rapidly proliferating cancers, further implicating ASF1B in tumor biology." (PMID 40944429, 2025). "For example, in CESC, LUSC, as well as STAD, ASF1B was markedly overexpressed in cancer tissues, while this overexpressed state predicted better overall survival." (PMID 38164276, 2024). "Overall, ASF1B is upregulated in a variety of human cancers, and is closely related to their prognosis." (PMID 38164276, 2024). "Anti-silencing function protein 1 homolog B (ASF1B) has been implicated in the occurrence and development of cancers." (PMID 36114946, 2023). "Consistently, comparison of ASF1B mRNA expression in cancer and matched paracancerous tissues from TCGA database demonstrated the upregulation of ASF1B in cancer." (PMID 35360875, 2022). "Compared to NAT, increased expression of ASF1b was reported in various cancer, and its high expression was predictive of poor prognosis." (PMID 35399734, 2022). "Accumulating evidence has shown that anti-silencing function 1b (ASF1b) contributes to the progression in multiple cancer types." (PMID 35399734, 2022). "Our research highlighted cell cycle regulation, as one of the major mechanisms of cell growth, was highly related to the promotion of cancer by ASF1b." (PMID 35399734, 2022). "Differential analysis of multiple databases showed that ASF1B was commonly and highly expressed in pan-cancer." (PMID 34490109, 2021). "We then investigated the relationship between ASF1B expression and TMB and MSI, both of which are strongly associated with sensitivity to immune checkpoint inhibitors (ICIs) across cancers." (PMID 34472711, 2021). "The detailed molecular mechanisms underlying the regulation of those key proteins by ASF1B need further explored in LUAD and other cancers." (PMID 34568067, 2021). "We investigated ASF1B expression levels in normal tissues and various cancer tissues using Oncomine." (PMID 34472711, 2021). "Our data provide novel insights into the functional importance of ASF1B in LUAD and indicate ASF1B as a potential target for the therapeutic management of cancers." (PMID 34568067, 2021). "Overall, our results indicated that ASF1B expression was significantly higher in 22 cancer types relative to normal tissues." (PMID 34472711, 2021). "Many genes play different roles in different cancers, thus explaining the variable prognostic significance of ASF1B observed among cancer types and subtypes." (PMID 34568067, 2021). "Overall, these data suggested that ASF1B serves as a tumor promoter and potential target for cancer therapy and provided us with clues to better understand the importance of ASF1B in many types of cancer." (PMID 34568067, 2021). "Studies have demonstrated that ASF1 regulates chromatin function and promotes cancer development, especially the ASF1B subtype, which has been reported as a promoter of multiple cancers." (PMID 34516341, 2021). "ASF1B expression was significantly positively correlated with DNA repair genes in all cancers except CHOL, LAML, UCS, and UVM." (PMID 34490109, 2021). "Gene coexpression analyses were further conducted to investigate correlations between ASF1B expression and immune‐related genes in 33 types of cancer." (PMID 34472711, 2021). "Asf1b also plays a key role in cell proliferation and has been used as a proliferation marker, especially in cancer diagnosis." (PMID 34906203, 2021).
cancer (continued). "The findings showed that immune cell infiltration levels were significantly correlated with the expression of ASF1B in most cancer types." (PMID 34472711, 2021). "At present, few studies have reported on the immunological role of ASF1B in cancer, and it is generally believed that ASF1B is a promoter of cell proliferation that can also act on the cell cycle." (PMID 34472711, 2021). "The onset and progression of cancer can be profoundly impacted by genetic and epigenetic changes, MSI, and TMB, and many of these mechanisms were correlated with ASF1B expression levels in different cancers in the present analysis." (PMID 34568067, 2021). "This work offers a basis for understanding the mechanism of action of ASF1B in various cancers and provides a rationale for targeting ASF1B with immunotherapies." (PMID 34472711, 2021). "In conclusion, our first pan‐cancer analysis of ASF1B shows that this gene is highly expressed in most tumor tissues compared to normal tissues and reveals an association between ASF1B expression and clinical prognosis." (PMID 34472711, 2021). "It’s found that ASF1B expression was significantly positively correlated with DNA repair genes in most cancers." (PMID 34490109, 2021). "The present study demonstrated that the ASF1B gene was highly expressed in 20 cancers; immunohistochemical (IHC) results supported this trend at the protein level." (PMID 34472711, 2021). "Previous studies have shown that Asf1b expression is abnormally high in cancer cells and closely related to cell proliferation." (PMID 34906203, 2021). "We further found that ASF1B expression was positively correlated with MSI in seven cancer types, including UCEC, STAD, SARC, LIHC, KIRC, ESCA, and BLCA, and negatively correlated with MSI in READ and LAML." (PMID 34472711, 2021). "It is worth noting that the most significant differences in ASF1B expression existed mainly between stage I and stage IV cancers." (PMID 34472711, 2021). "In this study, an integrated assessment of The Cancer Genome Atlas (TCGA) and genotype-tissue expression (GTEx) datasets revealed the overexpression of ASF1B in all analyzed cancer types other than LAML." (PMID 34568067, 2021). "The GSEA enrichment analysis revealed that ASF1B was involved in the regulation of many cancer metabolics and cancer immune signaling pathways." (PMID 34490109, 2021). "To further assess ASF1B expression across cancers, we used R software to analyze RNA sequencing data obtained from TCGA." (PMID 34472711, 2021). "We found that ASF1B was highly expressed in 22 cancers and was negatively correlated with the prognosis of multiple major cancer types." (PMID 34472711, 2021). "It’s found that ASF1B expression was significantly and positively correlated with methyltransferase in all cancer species except CHOL and UCS." (PMID 34490109, 2021). "Representative images and the quantified results indicated that ASF1B knockdown significantly suppressed cancer cell motility." (PMID 32848135, 2020). "In contrast, ectopic expression of ASF1B significantly accelerated cancer cell proliferation as evidenced by CCK-8 assay and induced cell growth according to colony formation assay." (PMID 32848135, 2020). "ASF1B is required for cell proliferation and is one of the most frequently overexpressed histone chaperones in cancer." (PMID 26655252, 2016). "Recent evidence also suggests that ASF1B may serve as a prognostic biomarker related to immunotherapy in several cancers." (PMID 40041497, 2025). "One major challenge is the ubiquitous expression of ASF1B in various cancer types, which may complicate the development of specific inhibitors without affecting normal cells." (PMID 40041497, 2025). "Subsequently, we investigated the effect of ASF1B expression on cancer prognosis." (PMID 38164276, 2024). "Furthermore, we also used the TIDE score to further explore the relationship between ASF1B and cancer immunotherapy response." (PMID 38164276, 2024).
cancer (continued). "Existing studies have given no definite explanation, and whether this is related to the different roles of ASF1B in different cancer contexts and different stages of cancer development needs to be further studied." (PMID 38164276, 2024). "In GEPIA2 analysis, we found that ASF1B expression could significantly affect the survival of 13 cancers." (PMID 38164276, 2024). "Surprisingly, in all of these 20 human cancers, ASF1B was highly expressed." (PMID 38164276, 2024). "Numerous studies have demonstrated that anti-silencing function 1B histone chaperone (ASF1B) is a key regulator of proliferation, apoptosis, and the cell cycle in different types of cancer and that its expression correlates with the clinical data and with the overall survival rates in particular." (PMID 39769169, 2024). "Similarly, it was reported that ASF1B was significantly correlated with poor prognosis in several other cancer patients." (PMID 37862114, 2023). "Therefore, our results, together with previously published studies, suggest that ASF1B acts as a cancer-promoting factor in the development of multiple cancers, providing a basis for the use of ASF1B as a therapeutic target for LGG or other cancers." (PMID 36947060, 2023). "Moreover, one of the human paralogs, Asf1B, is overproduced in most cancer tissues in comparison with normal ones." (PMID 36555405, 2022). "Recent studies have shown that ASF1B may be used as a new proliferation marker for cancer prognosis." (PMID 35360875, 2022). "ASF1B gene with the highest risk coefficient was selected to observe its expression and predictive value in THCA prognosis as well as in a variety of other cancers." (PMID 34490109, 2021). "We next sought to explore whether ASF1B expression patterns and prognostic relevance were related to patterns of DNA methylation in different cancer types." (PMID 34568067, 2021). "It is suggested that ASF1B may indirectly influence cancer development and progression by regulating epigenetic status." (PMID 34490109, 2021). "We used Oncomine to explore the expression levels of ASF1B in normal and various cancer tissues." (PMID 35087760, 2021). "In addition, immune activation genes and immunosuppressive genes were coexpressed with ASF1B in all cancer types, though the correlations were relatively small in CHOL, ESCA, PCPG, and USC." (PMID 34472711, 2021). "In addition, ASF1B expression was significantly and positively correlated with methyltransferases in many cancer species." (PMID 34490109, 2021). "Herein, we examined the expression and prognostic relevance of ASF1B across many cancer types." (PMID 34568067, 2021). "Overall, ASF1B is highly expressed in at least 22 types of cancers and high ASF1B expression may be a predictor of tumorigenesis." (PMID 34472711, 2021). "Additionally, Asf1b is highly expressed in multiple types of cancers including cervical cancer and prostate cancer and mainly involved in cell proliferation." (PMID 34906203, 2021). "Next, we examined the prognostic relevance of ASF1B in different cancer types in order to determine whether it was consistently associated with particular cancer patient outcomes." (PMID 34568067, 2021). "Our pan-cancer analysis similarly supported the function of ASF1B in the regulatory mechanism." (PMID 34490109, 2021). "The pan-cancer analysis suggested that ASF1B may play an important role in the tumor micro-environment and tumor immunity and it has the potential of serving as a predictive biomarker for multiple cancers." (PMID 34490109, 2021). "We conducted a pan‐cancer analysis of ASF1B using multiple databases, including Oncomine, HPA, CCLE, and TGCA, to characterize ASF1B expression and its correlation with prognosis, immune response, clinicopathology, and tumor microenvironment in diverse cancers." (PMID 34472711, 2021).
cancer (continued). "To further investigate the correlation between ASF1B expression and prognosis, we conducted survival correlation analyses in 33 cancers using the following metrics: overall survival (OS), disease‐free survival (DSS), disease‐free interval (DFI), and progression‐free interval (PFI)." (PMID 34472711, 2021). "Our findings show that ASF1B plays a vital role in cancer immunity." (PMID 34472711, 2021). "Therefore, we surmised that, in patients with these advanced cancers, high ASF1B expression was directly responsible for decreased survival." (PMID 34472711, 2021). "Furthermore, ASF1B expression is associated with TMB, MSI, and immune cell infiltration in various cancers." (PMID 34472711, 2021). "This indicates that ASF1B regulates cancer progression through these signaling pathways." (PMID 34568067, 2021). "This study showed that ASF1B was highly expressed in the majority of cancers." (PMID 34490109, 2021). "Furthermore, ASF1B expression was associated with TMB, MSI, and immune cell infiltration in various cancers." (PMID 34472711, 2021). "Recent studies have shown that anti-silencing function 1B (ASF1B) might be used as a new proliferation marker for cancer diagnosis and prognosis." (PMID 32848135, 2020). "Inhibition of ASF1B expression could decrease cell proliferation, indicating the potential of ASF1B to be a new target for treatment of cancer." (PMID 26655252, 2016). "This might indicate that ASF1B had different immune-related roles in different cancer contexts." (PMID 38164276, 2024). "The relationship between ASF1B and cancer immunity is largely unknown." (PMID 38164276, 2024). "Therefore, ASF1B may serve as a general oncogene to promote the malignancy phenotypes in different cancers." (PMID 36114946, 2023). "We hypothesize that SETD2-deficient cancer may be more sensitive to the inactivation of ASF1A and ASF1B than SETD2-proficient cancer if SETD2 loss–induced increase in histone exchange is required for creating a permissive epigenetic landscape to enhance oncogenic transcriptional output." (PMID 36810256, 2023). "Moreover, we induced the knockdown and overexpression of ASF1b to explore its function and mechanism, which revealed that the disrupting the ASF1b not only suppressed cancer cell proliferation in vitro but also slowed the growth of GC cell-derived xenograft tumors in vivo." (PMID 35399734, 2022). "Interestingly, above data demonstrated that targeting ASF1B may be an important method for cancer treatment." (PMID 34568067, 2021). "We used a range of bioinformatics approaches to investigate the predictive role of ASF1B, including its correlation with prognosis, tumor mutational burden (TMB), microsatellite instability (MSI), tumor microenvironment (TME), and immune cell infiltration, in diverse cancer types." (PMID 34472711, 2021). "However, the role of ASF1B in other cancer types remains uncertain." (PMID 34472711, 2021). "Therefore, we hypothesize that ASF1B may play a role in cancer development by regulating immune system‐related functions." (PMID 34472711, 2021). "Therefore, high ASF1B expression in certain cancers leads to decreased immune scores and may result in poor patient prognosis." (PMID 34472711, 2021). "Therefore, Asf1B may be recognized as an independent prognostic agent in multiple types of cancer." (PMID 36555405, 2022). "From a mechanistic point of view, ASF1B indirectly regulated CKS1B to mediate growth, apoptosis, and cell cycle progression in cancers." (PMID 35480879, 2022).
cancer (continued). "Western blotting was then performed to detect ASF1B protein expression in one normal liver cell line (LO2) and five HCC cancer cell lines (Hep3B, SMMC7721, MHCC97L, MHCC97H, and Huh7)." (PMID 35360875, 2022). "This study showed that ASF1B expression is correlated with TMB in 21 cancers and with MSI in 7 cancers." (PMID 34472711, 2021). "From our network, we observed that E2F1 regulates POLD1, ASF1B, FOXM1 and RACGAP1 which are up-regulated in all 15 cancer types (Subnetwork)." (PMID 30809433, 2019). "Although there is some evidence demonstrating that ASF1B plays a key role in the development, progression, and prognosis of certain cancers, there are no pan‐cancer analyses of ASF1B." (PMID 34472711, 2021). "No prominent correlation between age and ASF1B expression was observed in patients with other cancer types." (PMID 34472711, 2021). "ASF1B was significantly overexpressed in HCC, as in previous analyses of pan-cancer." (PMID 35087760, 2021). "Whether ASF1B expression was correlated with the level of immune infiltration in THCA, or other different types of cancers has been investigated." (PMID 34490109, 2021). "Overall, the results suggested that ASF1B may be a potential prognostic predictor in THCA and other cancers." (PMID 34490109, 2021). "Next, we measured ASF1B expression levels in different LUAD cell lines (A549, NCI-H1975, NCI-H1299, NCI-H1650) using data from the Cancer Cell Line Encyclopedia (CCLE) database, revealing that these levels ranged from low (A549 cells) to very high (H1650 cells)." (PMID 34568067, 2021). "In addition, studies have confirmed that the positively correlated co-expression genes NUSAP1, ASF1B, TPX2, and SKA1 are invariably involved in immune cell infiltration in numerous cancers, and thus contribute to the regulation of the tumor immune microenvironment." (PMID 38173030, 2024). "The protein expression of ASF1B in cancer tissues was higher than that in noncancerous tissues." (PMID 35360875, 2022). "Through molecular immune subtyping, we further observe significant differences in ASF1B expression levels across C1(wound healing), C1(IFN-γ dominant), C3(inflammatory), C4 (lymphocyte deplete), C5(immunologically quiet), and C6 (TGF-β dominant) subtypes for most analyzed cancers." (PMID 34568067, 2021). "Furthermore, we observed a negative correlation between ASF1B expression and M2 macrophages in all cancer types except LAML." (PMID 34472711, 2021). "Furthermore, ASF1B expression was correlated with TMB in 21 cancers and with MSI in 7 cancers." (PMID 34472711, 2021). "When we expanded these results to other tumors and normal tissue types, we found ASF1B to be unrelated to gamma delta T cell or activated memory CD4+ T cell infiltration in normal tissues, and it was similarly unrelated to naïve CD4+ T cell infiltration in analyzed cancers." (PMID 34568067, 2021). "We did not observe lower ASF1B expression in any of the 33 cancers relative to normal tissues." (PMID 34472711, 2021).